HIF1A (hypoxia inducible factor 1 subunit alpha)
Diseases named in the same sentence as HIF1A in open-access papers (continued):
Sharing a sentence is not in itself a finding about the gene and the disease.
cancer (continued). "The control of the HIF‐1α/NPM1 interaction by ERK‐dependent phosphorylation of HIF‐1α extends the role played by the ERK pathway both in normal and cancer cells." (PMID 34388291, 2021). "Perioperative risk factors including anesthetic use during surgery may contribute to cancer recurrence after surgery, which may be due to anesthetics; in particular, inhalational anesthetics significantly modulated cell signaling changes, including hypoxia inducible factor (HIF)-1α." (PMID 35280249, 2021). "It should be noted that besides HIF1α, HIF2α and VHL also play a role in cancer development and progression." (PMID 34209205, 2021). "In the attempt of counteracting the strong acidification, cancer cells up-regulate carbonic anhydrase (CA) IX and XII, both under the transcriptional control of HIF-1α." (PMID 33423689, 2021). "This is in line with results from other groups showing that estrogen can activate HIF-1α and that activation of HIF-1α stimulated HLA-G-expression in cancer cells." (PMID 35111157, 2021). "Western blotting analysis showed that both HIF-1α and JFK protein levels were significantly upregulated in the cancer tissue compared to the normal tissue." (PMID 34336836, 2021). "Since the expression levels of HIF-1α and GLUT1 were decreased by PDQ treatment and affected the energy supply of cancer cells, we investigated the glucose uptake of FaDu cells in response to PDQ treatment." (PMID 34281558, 2021). "HIF-1α stabilization can downregulate PDH expression and result in decreased Krebs cycle flux and oxygen consumption in hypoxic and cancer cells." (PMID 34858390, 2021). "It has been documented that 1,25(OH)2D3 decreases the expression of the HIF-1α subunit, VEGF and inhibits cancer cell proliferation under hypoxic conditions." (PMID 34208589, 2021). "Q-PCR was used to reveal that the transcriptional levels of STAT3-supporting cancer cell-intrinsic hallmarks, including BCL2, MMP9, HIF-1α and PIM1, were all decreased with SPATS2 knockdown in both MHCC-97H and HCC-LM3 cell lines." (PMID 33391405, 2021). "It promotes proliferation and metastasis of cancer cells and leads to a radioresistant phenotype via regulation of β-catenin/TCF and HIF-1α pathway." (PMID 34398824, 2021). "Through these redox modifications, ROS modulate the biological functions of proteins involved in ECM remodeling, for example, integrin, actin, NF-κB, HIF-1α or TGF-β, thereby regulating EMT initiation and cancer cell metastasis." (PMID 34502112, 2021). "As a messenger, ROS also affect several transcription factors, such as HIF1-α, NF-κB, AP-1, NRF2, which are important for cancer development." (PMID 33522955, 2021). "One of the key regulators of cell response to hypoxia is HIF1α, the activation of which leads to an increase in VEGF expression and through the VEGF-2 receptor to the enhancement of cancer cell growth and migration." (PMID 33546324, 2021). "We identify an immediate early transcriptional response that is strongly dependent on HIF1A and the kinase activity of its cofactor CDK8, includes indirect repression of MYC targets, and is highly conserved across cancer types." (PMID 33654095, 2021). "HIF-1 complex, consisting of two submits, the oxygen-sensitive HIF-1α and the constitutively expressed HIF-1β, participates in the cancer biology of numerous endocrine tumors." (PMID 34684168, 2021). "It is well known that MAPK and PI3K signaling pathways play an important role in regulating the expressions of HIF-1α and VEGF at the protein level in cancer cells 20-22." (PMID 34093799, 2021). "As a result, HIF-1α accumulates, translocates into the nucleus, dimerizes with HIF-1β, and transactivates several effector proteins involved in cancer cell migration and angiogenesis." (PMID 34680087, 2021).
cancer (continued). "This genetic upregulation of HIF-1α increases the vascular endothelial growth factor (VEGF) and promotes a metabolic switch in cancer and TME cells towards glycolysis (Warburg effect), which, in turn, promotes tumor angiogenesis and proliferation." (PMID 33451052, 2021). "LXY6090 reduces the level of HIF-1α target genes, such as VEGF and insulin-like growth factor 2 (IGF2), in vitro and the growth of cancer in vivo." (PMID 34575983, 2021). "Similar to HIF-1α, HIF-2α overexpression also correlates with poor prognosis in several cancer types (head and neck, brain, liver, colon, lung, bladder, kidney)." (PMID 34154610, 2021). "Both VEGF (vascular endothelial growth factor) and GLUT 1 (glucose transporter 1) are downstream targets of HIF-1α and play an important role in HIF-1α-induced cancer invasion." (PMID 34205571, 2021). "The deficiency of OGT reduces alpha-ketoglutarate levels, which is a metabolite essential for the degradation of HIF-1α via its hydroxylation by HIF-PHDs, indicating that upregulated O-GlcNAcylation enhances HIF-1α activity and cell survival in cancer cells." (PMID 33535386, 2021). "In cancer cells, VEGF is stimulated by HIF-1α and when these cells are exposed to melatonin, HIF-1α, VEGF and new vessel growth are hindered." (PMID 33466614, 2021). "Although HIF-1α and TARBP2 are both crucial for cancer development, the relationship between these two proteins remains to be clarified." (PMID 35008634, 2021). "CaMKII-dependent activation of hypoxia-inducible factor 1-alpha (HIF-1α) and P-glycoprotein prevents cancer cells from chemotherapy drug-induced cell death." (PMID 36045706, 2021). "TAT-conjugated TMC/TC/SPIONs containing siRNAs significantly reduced the HIF-1α and CD73 expression levels in cancer cells." (PMID 34502560, 2021). "The ICC assay results indicated that the expression of erythroid differentiation-related proteins, including HIF-1α, EPO, c-Myc, GATA-1, and GATA-2, was increased in cancer cells treated with ATO." (PMID 34676163, 2021). "As a cofactor of the transcription factor hypoxia-inducible factor 1 alpha (HIF1α), PKM2 plays an important role in the transcriptional control of glycolytic enzymes in cancer cells." (PMID 33959614, 2021). "HIF-1α, STAT3, and CBP/p300 are known as transcriptional complex components that regulate the response to hypoxia in cancer." (PMID 34692527, 2021). "This inhibitor suppressed the accumulation of HIF-1α and HIF-2α proteins in cancer cells by inhibiting mitochondrial complex I activity, but it did not pass the phase I clinical trials." (PMID 33445709, 2021). "In summary, our data demonstrated that MYC and HIF1α protein were degraded through proteasome dependent pathways, by the β-TrCP- and VHL-dependent mechanisms, respectively, in echinomycin-treated cancer cells." (PMID 33572152, 2021). "In cancer cells, sphingosine kinase 1 (SPHK1) is activated by reactive oxygen species (ROS) and increases AKT activity under hypoxia, eventually stabilizing HIF-1α proteins." (PMID 34575983, 2021). "Another study also demonstrated that Y6 reduces the activity of ERK and AKT and the level of HIF-1α and VEGF in hypoxic cancer cells." (PMID 34575983, 2021). "Magnolol can negatively control HIF-1α expression by interfering with the PI3K/AKT/mTOR pathway under hypoxia, hence suppressing angiogenesis and cancer growth in vivo." (PMID 34575983, 2021). "Our study revealed a lncRNA HIFAL played a critical regulatory role in HIF-1α-driven transactivation and glycolysis, supporting HIFAL as a therapeutic target for cancer treatment." (PMID 33637716, 2021).
cancer (continued). "In terms of anti-cancer mechanism, CTP/CDDP was able to decrease efflux and increase intracellular retention of CDDP by reducing the expression of HIF-1α, GSH and MRP2, thus relieving the chemotherapeutic drug resistance." (PMID 34399762, 2021). "As already mentioned, phosphorylation of Ser641/643 in the ETD domain of HIF-1α by p42/44 MAPK (ERK1/2), which are often activated in human cancers, is essential for HIF-1α nuclear accumulation and activity because it masks a CRM1-dependent NES." (PMID 33499237, 2021). "Treatment of cancer cells with LW6 induces VHL expression, leading to the degradation of the HIF-1α protein." (PMID 34200019, 2021). "It has been noticed that the expression of HIF-1a and HIF-2a is stronger in cancer than in normal tissues." (PMID 34575983, 2021). "We showed that combining acriflavine, reported as a pharmacological agent preventing HIF-1α/HIF-1β dimerization, dramatically improved the benefit of cancer immunotherapy based on TRP-2 peptide vaccination and anti-PD-1 blocking antibody." (PMID 34155342, 2021). "TRPC5 is elevated in colon cancer, which promotes cancer cell EMT and metastasis via the HIF-1α/Twist axis." (PMID 36046433, 2021). "The mechanism of LDHA-induced chemoresistance can be summarized as follows: First, as a direct target of the HIF-1A and C-MYC oncogenes, LDHA promotes biosynthesis and glycolysis, ensuring energy supply and proliferation of cancer cells." (PMID 34540667, 2021). "In fact, the cancer cells have the ability of adaptation to hypoxia through the regulation of the PI3K/AKT/mTOR pathway and by the transcription factors HIF-1α and HIF-2α, whose protein expression and transcriptional activity are also regulated by mTOR." (PMID 33669301, 2021). "Several studies have demonstrated that hypoxia inducible factor 1A (HIF1A) and its downstream genes (e.g., GLUT1, VEGF, CA9) are also poor prognostic markers for various cancers." (PMID 34439934, 2021). "Besides, the impact of the E6 and E7 variants of HPV 16 on metabolic reprogramming through proteins such as HIF-1α may be related to their oncogenicity by favoring cellular metabolism modifications to satisfy the energy demands necessary for viral persistence and cancer development." (PMID 33809480, 2021). "We performed a computational analysis in more than 450 human cancer cell lines to compare gene expression levels of PERK, NRF2, and HIF-1α." (PMID 33441543, 2021). "Previously, Hypoxia-inducible factors (HIFs, including HIF1α and HIF2α) and several oncogenic proteins (AKT, FOXK1/2, SIX1, and c-MYC) are broadly expressed in human cancers and have been reported to be involved in the regulation of the Warburg effect." (PMID 33832535, 2021). "For example, when HIF-1α is enhanced, H2O2 is administered to the hypoxic part of the cancer tissue to supply oxygen or H2O2 like KORTUC, and activate ferroptosis, administrate iron, enhance glycolysis, remove glucose and administrate galactose." (PMID 34361070, 2021). "HIF-1α and NF-κB signaling have been verified to individually induce EMT in several kinds of cancers." (PMID 34073155, 2021). "In vitro studies have demonstrated that HIF1α regulates LncRNA-NEAT1 transcription, maintaining cancer cell growth and inhibiting their apoptosis and cell cycle arrest." (PMID 34359789, 2021). "Many cancer- and inflammation-related transcription factors, as NF-κB, HIF1α, TGFβ, TNFα are involved in the transcriptional regulation of CLU during cancer progression." (PMID 34360868, 2021).
cancer (continued). "Similar kinds of manifestations were also noted in toxic control after MNU administration, i.e., the increase in HIF-1α, SREBP-1c, FASN but a decrease in PHD-2, which indicated the development of cancer hypoxia in these animals." (PMID 34090331, 2021). "It has also been recognized that HIF-1α can actually improve function of some immune cells; therefore, exploration of HIF modulation in terms of improving immune recognition of cancer is an active area of research." (PMID 34746010, 2021). "It has been shown that HIPK2 can suppress HIF1α/VEGF signaling to decrease angiogenesis and the degradation of HIPK2 leads to enhanced HIF1α/VEGF signaling and angiogenesis is a key mechanism of cancer progression." (PMID 34963484, 2021). "Due to their ability to directly activate transcription of target genes, an increased expression of HIF-1α and HIF-2α was reported in a variety of human cancers and was correlated with a switch versus a more aggressive phenotype." (PMID 34944758, 2021). "The expression of HSP90α, HIF1α and RIPK1 was stronger in cancer tissues than in liver tissues; however, RIPK3 was expressed more in liver tissues." (PMID 33440739, 2021). "Further, consistent with its role in angiogenesis during cancer development, HIPK2 acted as a suppressor of angiogenesis in DR as well by negatively regulating HIF1α/VEGF signaling." (PMID 34963484, 2021). "Previous laboratory research work by us and other groups has shown that digoxin induces cancer cell apoptosis, and it targets not only NKA but also HIF-1α and NF-κB to mediate its antitumor potential." (PMID 34208576, 2021). "In both cancer entities, AKT further promotes the expression of CXCR4 via stabilization of the transcription factor HIF-1α." (PMID 34064589, 2021). "Our results furthermore confirm our recently proposed K-Ras-directed HIF1α and Gal3-dependent mechanism of action of Hsp90 inhibitors, suggesting that KRAS mutant cancers should be considered for the evaluation of Hsp90 inhibitors in the future." (PMID 34199986, 2021). "Several KDMs play an active role in metabolic rewiring in cancer, for example, KDM3A/JMJD1A, which promotes BC progression by enhancing glycolysis through the coactivation of HIF-1α." (PMID 34072826, 2021). "Increased gene expression of HIF-1 (HIF-1α and HIF-1β complex) is known to be present in 53% of all types of cancer, and in 56–76% of breast cancers." (PMID 33888756, 2021). "Hypoxia increases HIF-1α expression and the mechanisms by HIF-1α target genes led to poorer patient survival through decreasing apoptosis, enhancing cancer cell survival and induction of angiogenesis." (PMID 33546453, 2021). "Herein, based on previous reports regarding PI3K/Akt/mTOR pathway regulating HIF-1α and HIF-1α promoting Zeb1 expression, we investigated the possible role of neddylation between HIF-1α and ZEB1 regarding cancer cell migration." (PMID 33097763, 2020). "But interestingly the relative increase in HIF1α from the untreated control was approximately 26–30 fold in MCF10A cells and only 3–4 fold in the cancer cells." (PMID 31980706, 2020). "The HIF family, particularly the isoforms HIF1-α and HIF2-α, are important targets, especially in aggressive forms of cancer where drug resistance interferes with therapy." (PMID 32605023, 2020). "Both HIF-1α and HIF-2α have been demonstrated to play essential roles in monocyte recruitment and macrophage differentiation in many cancers, including HCC." (PMID 33400730, 2020).
cancer (continued). "In addition, CDK2 positively regulates HIF-1α transactivity in cancer cells, and it was postulated that CDK2 could uncouple the transcriptional and non-transcriptional functions of HIF-1α in a manner analogous to the well-characterised mechanism involving cMYC and SKP2." (PMID 33383924, 2020). "Digoxin was reported to inhibit HIF-1α protein synthesis and expression of HIF-1 target genes in cancer cells, and therefore block primary tumor growth, vascularization, invasion, and metastasis." (PMID 32180730, 2020). "Intriguingly, PKM2 interacts with HIF-1α physically and functionally to stimulate the binding of HIF-1α at target genes and promotes HIF-1α transcriptional activity in human cancer cells." (PMID 33376737, 2020). "For example, the PI3K/Akt/mTOR pathway can regulate the expression of HIF-1α, and the inhibition of this pathway down-regulates HIF-1α expression, thereby enhancing the sensitivity of MDR cells to cancer treatment." (PMID 32974385, 2020). "Another miRNA, miR-23a/b is delivered from adipocytes to cancer cells, and miR-23a/b was shown to act to modulate HCC cells by repressing the expression of VHL/HIF-1α." (PMID 33297338, 2020). "A reduced expression of PHD1/2 leads to an increase of HIF‐1α signalling, higher VEGF expression and augmented angiogenesis in hypo‐EV miR‐23a exposed cancer cells." (PMID 33304471, 2020). "Given a well-established role of HIF-1α in tumorigenesis, some inhibitors have been developed to target HIF-1α in a wide variety of cancers." (PMID 33266219, 2020). "This study elucidated that the low PD-LI expression in OSCC correlated with cancer aggressiveness, poor prognosis, high 18F-FDG-uptake with HIF-1A/GLUT1 expression, low E-cadherin expression and low CD8+TILs." (PMID 32238919, 2020). "While PIN1 overexpression in cancer has been correlated with increased HIF-1α stability, the inverse is suggested to occur with AD whereby PIN1 promotes HIF-1α degradation via a GSK-3β-dependent mechanism." (PMID 33383924, 2020). "Actually, studies have confirmed that activation of PPARα suppressed HIF-1α signaling in human breast (MCF-7) and ovarian (A2780) cancer cells under hypoxia." (PMID 32963130, 2020). "We also see CTNNB1, KLF4, HIF1A, and MYC as particularly important across many cancers as well as evidence to suggest substantial cross-talk and perhaps overlap." (PMID 33106165, 2020). "HIF-1α plays a significant role in invasion and metastasis of cancer cells and AE treatment attenuated invasion and metastatic properties of HGSOC cells, therefore, we determined the effect of AE on the expression of HIF-1α protein in all HGSOC cell lines." (PMID 32194804, 2020). "In this context, numerous studies rank miRNA-210 among the major influenced miRNAs under hypoxic conditions and were able to show a direct regulation of miRNA-210 by a HIF-1α-dependent pathway in PDAC and other cancer entities." (PMID 33113836, 2020). "Indeed, evidence has been obtained in cancer cells that Nrf2 may directly regulate the expression of HIF1A, the gene encoding HIF-1α, while in cardiomyocytes HIF-1α upregulation has been reported to be related to Nrf2 activation through heme oxygenase-1 (HO-1) expression." (PMID 32545222, 2020). "Low expression of PD-L1 in OSCC correlated with cancer aggressiveness, poor prognosis, high 18F-FDG-uptake with HIF-1A/GLUT1 and low E-cadherin expression and low CD8." (PMID 32238919, 2020). "HIF-1α activates transcription factors, such as Snail, twist, and ZEB1, under hypoxic conditions, promoting EMT pathogenesis and leading to cancer cell acquisition of stem cell activity." (PMID 33062005, 2020). "We found that both HIF‐1α and HIF‐2α (EPAS1) have the ability to activate oncogenes deeply involved in cancer biology, such as VEGF, CXCL8 and PGR." (PMID 32537867, 2020).